NGLY1 (N-glycanase 1)
Diseases named in the same sentence as NGLY1 in open-access papers (continued):
Sharing a sentence is not in itself a finding about the gene and the disease.
genetic disorder (16 papers, 2016 to 2025). "A genetic disorder caused by mutations in the NGLY1 gene leads to NGLY1 deficiency with symptoms including motor deficits and neurological problems." (PMID 38417795, 2024). "NGLY1 deficiency is an ultra-rare, autosomal recessive genetic disease caused by mutations in the NGLY1 gene encoding N-glycanase one that removes N-linked glycan." (PMID 36875753, 2023). "Accumulating evidences point out that NGLY1 deficiency can cause an autosomal recessive (AR) human genetic disorder with abnormal development, indicating its critical functions for the normal development of mammals." (PMID 35565658, 2022). "Accumulating evidence also points out that NGLY1 deficiency can cause an autosomal recessive (AR) human genetic disorder associated with abnormal development and congenital disorder of deglycosylation." (PMID 35565658, 2022). "Interest in NGLY1 has been focused on its central role in the rare genetic disorder NGLY1 deficiency and in its importance towards cellular glycoprotein turnover." (PMID 34995415, 2022). "Identification of a second patient with similar phenotypes and harboring NGLY1 variants in 2013 established NGLY1 deficiency as a new rare genetic disorder." (PMID 35406718, 2022). "Our study also identified the CNS as a potential therapeutic target organ for NGLY1 deficiency, and i.c.v. administration as a promising administration route for treatment of this genetic disorder." (PMID 34120625, 2021). "Our discoveries serve as a vivid proof for the high value of understanding the biology hinted at by a rare genetic disorder like NGLY1 deficiency." (PMID 30385822, 2018). "A genetic disorder, NGLY1-deficiency, caused by mutations in the NGLY1 gene has recently been discovered." (PMID 28426790, 2017). "NGLY1, the human PNG-1 orthologue, plays important roles in human development; NGLY1 deficiency, a recently described genetic disorder of protein deglycosylation, is caused by mutations at the NGLY1 locus." (PMID 27528192, 2016). "NGLY1 deficiency is a rare genetic disorder caused by mutations in the NGLY1 gene." (PMID 40811347, 2025). "Since the discovery of NGLY1 deficiency, Ngly1 research has accelerated around the world with the aim of elucidating the detailed molecular mechanism responsible for its pathogenesis as well as establishing therapeutic options for this genetic disorder." (PMID 41203122, 2025). "NGLY1 deficiency is a genetic disease caused by biallelic mutations of the Ngly1 gene." (PMID 38649481, 2024). "Since the identification of a patient with an autosomal recessive genetic disorder caused by NGLY1 gene dysfunction, known as NGLY1 deficiency or NGLY1 congenital disorder of deglycosylation (OMIM: 615273), in 2012, more than 100 cases have been reported worldwide." (PMID 39206713, 2024). "Furthermore, NGLY1 deficiency is a rare genetic disorder with a complex clinical presentation which often includes neurological symptoms and developmental delay." (PMID 34995415, 2022). "Although loss of NGLY1 is responsible for a rare human genetic disorder, and the range of its substrates necessitate thorough characterization, inhibiting NGLY1 might serve as another druggable target in this pathway." (PMID 32033280, 2020). "In any event, the phenotypes observed for Ngly1−/− and Ngly1−/−;Engase−/− mice were found to be very analogous to the symptoms observed in patients with an NGLY1-deficiency, which make those mice valuable animal models for this genetic disorder." (PMID 28426790, 2017).
cancer (11 papers, 2012 to 2025). A tumor composed of atypical neoplastic, often pleomorphic cells that invade other tissues. "Despite the recently gained knowledge about NGLY1 deficiency, there is limited information regarding the responses of human cancer cells and terminally differentiated somatic cells to NGLY1 suppression." (PMID 30385822, 2018). "Loss of NGLY1 sensitizes nematodes and human cancer cell lines to proteasome inhibition." (PMID 29735526, 2018). "In fact, they showed that chemical inhibition of NGLY1 function potentiates cytotoxicity caused by proteasome inhibition in human cancer cell lines, which mirrors the observation in nematodes that png-1 loss-of-function mutants are extremely hypersensitive to proteasome inhibition by bortezomib." (PMID 29735526, 2018). "Moreover, cancer cells, at least in certain cancer types, may be particularly vulnerable to loss of NGLY1 compared with normal cells." (PMID 30385822, 2018). "NGLY1 inhibitors have demonstrated not only antiviral properties but also significant implications in cancer treatment." (PMID 38067490, 2023). "Together, these studies establish NGLY1 as a potential therapeutic target in several forms of cancer." (PMID 35406718, 2022). "Not only is NGLY1 essential in a variety of cells, it plays a crucial role in cancer development by being expressed in many types of cancer cells." (PMID 35294432, 2022). "Although NGLY1 is known as a pivotal enzyme that catalyses the deglycosylation of denatured glycoproteins, information regarding the responses of human cancer and normal cells to NGLY1 suppression is limited." (PMID 30385822, 2018). "Further, inhibitors of NGLY1 or DDI2 may synergize with proteasome inhibitor drugs for treatment of some cancers." (PMID 38991033, 2024). "Accordingly, the Bertozzi lab hypothesized that NGLY1 inhibitors might further sensitize cancer cells to proteasomal inhibitors, thereby offering novel tools for combination therapy with proteasomal inhibitors." (PMID 35406718, 2022). "Our study suggests that alterations in O-GlcNAc and NGLY1 could be future targets utilized as therapeutics for nutrient-sensitive stem cell-derived diseases such as cancer." (PMID 35294432, 2022). "Inhibition of NGLY1 has been shown to adversely impact cancer cell viability, however the ddVenus reporter could be inhibited through alterations to its translation, translocation, or degradation through another means." (PMID 32265286, 2020). "Nrf1, NGLY1, and DDI2 are co-essential in some cancer cell lines, suggesting that Nrf1-dependent regulation of the proteasome promotes proliferation of cancer cells." (PMID 38991033, 2024).
movement disorder (10 papers, 2020 to 2025). Neurological conditions resulting in abnormal voluntary or involuntary movement, which may impact the speed, fluency, quality and ease of movement. "This is an important finding since patients with NGLY1 deficiency display symptoms related to movement disorder." (PMID 36875753, 2023). "Since the midbrain area of the brain controls the motor system and is implicated in movement disorders like Parkinson’s disease, we reasoned that a midbrain organoid model would help us understand how NGLY1 deficiency may cause a movement disorder." (PMID 36875753, 2023). "Moreover, this study demonstrated that the zebrafish is a powerful tool for studying NGLY1 deficiency, since the mutant fish featured a unique combination of clinical hallmarks of the disease, including global developmental delay, movement disorders and eyes abnormalities." (PMID 40470739, 2025).
infection (7 papers, 2009 to 2024). The state of being infected such as from the introduction of a foreign agent such as serum, vaccine, antigenic substance or organism. "siRNA knockdown of NGLY1 or Z-VAD-FMK (benzyloxycarbonyl-Val-Ala-Asp-fluoromethyl ketone) inhibits NGLY1, restricting the infection of enterovirus 71 (EV71) and coxsackievirus A16 (CA16) in RD cells." (PMID 38067490, 2023). "siRNA knockdown of NGLY1 restricted the infection of EV71 in both RD and SK-N-SH cells and also inhibited the replication of CA16 in RD cells." (PMID 27748395, 2016). "However, the endoplasmic reticulum (ER)-associated degradation (ERAD) components, N-glycanase 1 (NGLY1), and valosin-containing protein (VCP) were identified as host-supportive factors that facilitate EV-A71 infection and replication." (PMID 33381104, 2020).
tumor (5 papers, 2018 to 2025). "Elevation of NGLY1 was observed in patients’ tumor samples, suggesting a function in oncogenic signaling." (PMID 35294432, 2022). "The enhanced expression of GADD153, IRF3 and IL-29 was also detected in the NGLY1-knockdown tumours." (PMID 30385822, 2018). "The significant upregulation of NGLY1 was also observed in patients’ tumour samples." (PMID 30385822, 2018).
neurodegenerative disease (4 papers, 2021 to 2025). A disorder of the central nervous system characterized by gradual and progressive loss of neural tissue and neurologic function. "Since aggregation of amyloids is a mechanism underlying several neurodegenerative diseases, repurposing drugs already approved to treat other neurodegenerative diseases may be cost effective and applicable for the treatment of NGLY1‐deficient patients." (PMID 40470739, 2025). "The proof of concept demonstrated by targeting the STING pathway with an orally bioactive STING antagonist VS-X4 paves new avenues for therapeutic interventions, not only for NGLY1 deficiency but also for other neurodegenerative diseases involving the STING pathway." (PMID 40644312, 2025). "We present a Ngly1-deficient mouse model on the C57BL/6 background that is genetically trackable and develops progressive neurodegenerative disease." (PMID 40644312, 2025). "Together, these results provide preclinical evidence that targeting the STING pathway with an orally bioactive antagonist could be an effective treatment for NGLY1 deficiency and potentially for many other STING-associated neurodegenerative diseases." (PMID 40644312, 2025).
neurological disease (3 papers, 2022 to 2025). "Given that neurological diseases are the primary clinical manifestations in NGLY1 deficiency patients, we next investigated the underlying neuropathology in iNgly1−/− mice." (PMID 40644312, 2025). "Using the iNgly1 mouse model, we provide genetic and pharmacological evidence to demonstrate that the STING pathway plays a crucial role in the development of neurological disease associated with Ngly1 deficiency in mice." (PMID 40644312, 2025). "However, tissue-specific deletion of Ngly1 in Purkinje cells or microglia alone is insufficient to induce Purkinje cell loss or neurological disease." (PMID 40644312, 2025). "Recently, several groups engineered AAV capsids to cross the BBB more efficiently than AAV9 in mice or nonhuman primates (NHPs), potentially enabling noninvasive systemic gene therapy development for myriad neurological disorders afflicting broad CNS regions, such as NGLY1 deficiency." (PMID 39137042, 2024). "In this study, we generated a postnatal inducible whole-body Ngly1 knockout mouse model that develops progressive neurological disease." (PMID 40644312, 2025). "Clinical translation of IV rAAV gene therapy for neurological diseases such as NGLY1 deficiency is not without challenges." (PMID 39137042, 2024).
peripheral neuropathy (2 papers, 2020 to 2025). A disorder affecting the peripheral nervous system. "Axonal degradation in the sciatic nerves, an indicator of peripheral neuropathy, which is frequently observed in human patients, was also seen in Ngly1−/− rats." (PMID 32259258, 2020).
neurodevelopmental disorder (1 paper, 2020). A behavioral and cognitive disorder with onset during the developmental period that involves impaired or aberrant development of intellectual, motor, or social functions. "NGLY1-CDDG is a multisystemic neurodevelopmental disorder (Online Mendelian Inheritance in Man: 615273)." (PMID 32576142, 2020).
neuromuscular disease (1 paper, 2020). "N-Glycanase 1 (NGLY1) deficiency is an ultra-rare, complex and devastating neuromuscular disease." (PMID 32265286, 2020).
NGLY1 also shares sentences with these, for which no sentence is quoted: multiple myeloma (4 papers); scrapie (3); Osteopenia (2); ovarian carcinoma (2); Alzheimer disease (1); anemia (1); Ataxia (1); Athetosis (1); bacterial infection (1); bladder cancer (1); breast carcinoma (1); Cerebellar atrophy (1); cerebral palsy (1); cervical cancer (1); Chorea (1); colorectal cancer (1); cutis laxa (1); dilated cardiomyopathy (1); Dysmetria (1); dysplasia (1); Dystonia (1); epilepsy (1); frontotemporal dementia (1); gastric carcinoma (1); glioma (1); hypothyroidism (1); learning disability (1); leukocyte adhesion deficiency type II (1); lipodystrophy (1); Lissencephaly (1).
A further 16 diseases each share a sentence with NGLY1 in 1 paper.